TRPC6 (transient receptor potential cation channel subfamily C member 6)
Diseases named in the same sentence as TRPC6 in open-access papers (continued):
Sharing a sentence is not in itself a finding about the gene and the disease.
glomerular diseases (continued). "Collectively, these data suggest that some amount of TRPC6 (and/or TRPC3) activity contributes to the formation of normal glomeruli or their subsequent function but that sustained hyperactivation of TRPC6 also leads to glomerular disease." (PMID 36421724, 2022). "TRPC6 channels also appear to play a role in driving glomerular disease in aging and in autoimmune glomerulonephritis." (PMID 35805070, 2022). "It was subsequently shown that expression of wild-type TRPC6 proteins and transcripts is increased in patients with acquired forms of glomerular disease, including FSGS and minimal change disease." (PMID 35805070, 2022). "Several studies to test this idea have made use of TRPC6 knockout models in mice and rats and have examined models of acquired forms of glomerular disease." (PMID 36421724, 2022). "These animal models will provide a conclusive answer about the role of TRPC6 in the context of glomerular diseases and podocyte injury." (PMID 34830371, 2021). "In summary, the discovery that gain-of-function mutations in TRPC6 caused familial forms of FSGS generated significant interest in targeting TRPC6, and perhaps other TRPC family members, to treat glomerular disease processes." (PMID 31877991, 2019). "Since the discovery that mutations in TRPC6 caused familial forms of FSGS, over 50 genes have been linked to inherited causes of glomerular disease." (PMID 31877991, 2019). "While TRPC6 inhibitors remain plausible targets for some glomerular diseases, for example in certain forms of FSGS,1, 25, 27 the data from animal models of DN are much less encouraging." (PMID 32123821, 2019). "Pharmacologic inhibition of either TRPC6 activity or expression has also been shown to ameliorate glomerular disease in animal models of FSGS." (PMID 31877991, 2019). "While we cannot exclude a role for TRPC6 in immunomodulation in PAN nephrosis, FSGS is generally considered to be a podocyte disease, and there is a report that podocyte-specific over-expression of TRPC6 results in glomerular disease in mice." (PMID 29785489, 2018). "In this regard, there is evidence that TRPC6 channels are acutely protective in an inflammatory milieu, for example during complement-mediated glomerular disease." (PMID 27630573, 2016). "Consistently with these findings, we have previously reported that high levels of wild-type Trpc6 expressed specifically in podocytes also trigger a glomerular disease presenting with signs of FSGS." (PMID 34012910, 2015). "Up-regulated TRPC6 protein expression occurs in many human glomerular diseases and in animal models of renal disease." (PMID 25393730, 2014). "TRPC6 might also play a pro-inflammatory role in glomerular diseases that are characterized by the deposition of immune complexes on the GBM, e.g., systemic lupus erythematosus (SLE)." (PMID 38003608, 2023). "Based on these lines of evidence, TRPC6 might be involved in the pathogenesis of glomerular diseases that are characterized by glomerular infiltration of neutrophils, macrophages or T-cells, such as I/R, DN, and glomerulonephritis." (PMID 38003608, 2023). "In addition, podocyte TRPC6 is well-known as being involved in podocyte injuries and glomerular disease by mediating deleterious intracellular signaling pathways and podocyte cytoskeletal rearrangements." (PMID 38003608, 2023). "Drugs that affect the activation of TRPC6 through effects on the local membrane environment could represent a therapeutic strategy for certain glomerular diseases." (PMID 36429053, 2022). "In addition to lipid dynamics, there is now an extensive body of evidence depicting that sustained increases in the TRPC6 activity can contribute to the progression of multiple forms of glomerular disease." (PMID 36429053, 2022). "In summary, introducing a gain-of-function mutation, corresponding to a human FSGS disease mutation, into murine Trpc6 fails to recapitulate the human glomerular disease pathology." (PMID 35913909, 2022).
glomerular diseases (continued). "In the study, we focused on TRPC6, a Ca2+-permeable non-selective cation channel, which is strongly associated with glomerular diseases." (PMID 36213244, 2022). "In addition, Riociguat seems to have therapeutic potential for proteinuric glomerular diseases by interfering with injurious TRPC6 signaling." (PMID 34830371, 2021). "We reason that these drugs might also hold therapeutic potential for glomerular diseases by interfering with injurious TRPC6 signaling in the podocyte." (PMID 34830371, 2021). "Inhibition of TRPC6 may be therapeutically useful in some glomerular diseases, but the overall effects of TRPC6 inactivation or knockout appear to be disease model-dependent and are probably also strain- and species-dependent." (PMID 33918778, 2021). "Excessive entry of Ca2+ into podocytes via TRPC6 may lead to podocyte injury and apoptosis in various forms of glomerular diseases, including DKD." (PMID 33321755, 2020). "Taken together, these data suggest that repurposing currently approved PDE inhibitors may be useful for the treatment of glomerular diseases by inhibiting both TRPC6 expression and activity." (PMID 31877991, 2019). "A role for TRPC6 in primary glomerular disease processes was first suggested by Reiser and colleagues, who demonstrated that TRPC6 was upregulated in microdissected glomeruli in human kidney biopsy specimens from patients with MGN and MCD, with a similar trend in patients with FSGS." (PMID 31877991, 2019). "Therefore, we provide evidence demonstrating the critical role of Ang II/TRPC6 axis in the control of glomeruli function, which is likely important for the development of glomerular diseases." (PMID 28331185, 2017). "Given the involvement of GMC apoptosis in glomerulopathy, we propose that mesangial derangement promoted by TRPC6-dependent [Ca2+]i elevation and subsequent cell death may be of importance in renal dysfunctions, especially in immature kidneys." (PMID 27383564, 2016). "Uncertainty exists on whether TRPC6 mutations need a genetic or environmental trigger to induce glomerular disease in mice, or if mice are intrinsically not suitable to model TRPC6-mediated human FSGS." (PMID 37615749, 2023). "It remains unclear if Trpc6 mutations require an as yet unidentified environmental or genetic hit to induce glomerular disease in mice, or if mice are intrinsically not suitable to model TRPC6-mediated human FSGS." (PMID 35913909, 2022). "Therefore, it is notable that wild-type TRPC6 channels may be dysregulated in acquired forms of glomerular disease." (PMID 36421724, 2022). "On the basis of our findings in Gq mice, we next crossed our TG animals with the whole body TRPC6 knockout mice and treated the animals with PAN to induce glomerular disease." (PMID 31877991, 2019). "Although TRPC6 has been a major focus for drug discovery, more recent studies suggest that other TRPC family members play a role in the pathogenesis of glomerular disease processes and chronic kidney disease (CKD)." (PMID 31877991, 2019). "Mutations in the genes that code for proteins that are expressed in podocytes including nephrin, podocin, WT1, α-actinin-4, inverted formin 2 (INF2), TrpC6, MYH9, and phospholipase Cε1, lead to glomerular disease." (PMID 27942003, 2016). "Thus, TRPC6 may be an important downstream gene target of CN signaling in glomerular disorders." (PMID 25429282, 2014). "Signaling via the non-selective cation channel TRPC6 in podocytes is crucial in genetic and sporadic glomerular disease." (PMID 36672207, 2023). "Nevertheless, the data presented herein provide evidence that the modification of membrane stiffness influence TRPC6 signaling and may represent a therapeutic approach for DKD and potentially other glomerular diseases in the future." (PMID 36672207, 2023). "Although Gq signalling was shown to mediate the effects of TRPC6 in glomerular disease, the role of Gi has never been studied in the podocytes and in the context of kidney disease." (PMID 35678269, 2022).
glomerular diseases (continued). "TRPC6 activation also contributes to the pathogenesis of glomerular diseases by mechanisms that are independent of calcineurin activation." (PMID 31877991, 2019). "However, the differing effects of TRPC6 knockout in animal models of NTS, FSGS, and diabetic kidney disease suggest that targeting TRPC6 to treat glomerular disease processes is likely to be disease-specific." (PMID 31877991, 2019). "An important observation was that TRPC3 is upregulated in glomerular diseases in a fashion similar to TRPC6, with no change in expression of TRPC5." (PMID 31877991, 2019). "In contrast, TRPC6 was a classical signaling molecule, an ion channel, which might play an important role in non-familial forms of glomerular disease." (PMID 31877991, 2019). "In both hereditary and nonhereditary glomerular diseases, TRPC6 gain-of-function induces massive calcium influx into podocytes, and aberrant calcium levels disrupt the filtration barrier, promote the rearrangement of the highly dynamic podocyte actin cytoskeleton, and induce proteinuria." (PMID 25393730, 2014). "However, some studies have suggested that TRPC6 (over)expression could also protect podocytes against complement-mediated glomerular disease and that TRPC6 knock-out was not protective in a specific model of diabetic nephropathy." (PMID 34830371, 2021). "Patients with non-familial glomerular diseases, including primary FSGS, express TRPC6 at higher levels within glomeruli." (PMID 29785489, 2018). "In nongenetic forms of glomerular disease, such as minimal change disease (NCD), membranous glomerulonephritis (MGN), and FSGS, TRPC6 overexpresion can directly affect cytoskeletal organization in podocytes." (PMID 22545060, 2012).
breast carcinoma (35 papers, 2008 to 2025). "In breast cancer patients, genetic variants at TRPC6 have been associated with doxorubicin-induced cardiomyopathy and congestive heart failure." (PMID 35096991, 2021). "That study identified transient receptor potential cation channel subunit 6 (TRPC6) as a potential risk locus for doxorubicin-induced cardiomyopathy in patients with breast cancer." (PMID 35096991, 2021). "In lowly metastatic breast cancer cell line MCF-7 the predominant channel expressed was a short splice variant of TRPC6." (PMID 19689790, 2009). "Therefore, our observations of the pleiotropic effects of Trpc6-deficiency in female mice in relation to doxorubicin treatment may be of clinical relevance to the efficacy of doxorubicin in breast cancer patients." (PMID 35096991, 2021). "TRPC6 is being explored as a biomarker for cardiotoxicity in breast cancer (NCT05507879), while TRPV6 is currently in phase I trial for advanced ovarian cancers (NCT01578564)." (PMID 40813985, 2025). "TRPC6 has been found to be overexpressed in breast cancer biopsy tissues compared to normal breast tissues." (PMID 37892239, 2023). "Human breast cancer cells in vitro also display significant levels of TRPC6 expression, and its silencing results in a significant reduction in cell growth." (PMID 37892239, 2023). "One observational study (NCT05507879) evaluates the role of TRPC6 as a predictive biomarker of chemotherapy-related cardiac toxicity in patients with breast cancer." (PMID 37892239, 2023). "The expression of TRPC6 is also found to be higher in gastric, ovarian, prostate, liver, and breast cancers than it is in normal tissues." (PMID 35392906, 2022). "TRPC3 expression correlates with the differentiation grade of non-small cell lung cancer, and abnormal upregulation of TRPC3 and TRPC6 has been reported in breast cancer tissues." (PMID 35216080, 2022). "Both studies further demonstrated reductions in breast cancer cell invasiveness in response to activation of either TRPC1 (PEMF exposure) or TRPC6 (Furin inhibition)." (PMID 35141145, 2021). "In breast cancer cells, Orai1 and TRPC6 are upregulated in the estrogen receptor positive (ER+) and triple negative subtypes, and Orai3 is overexpressed exclusively in the ER+ breast cancer subtype." (PMID 34439314, 2021). "While other studies reported that TRPC6 overactivation mediated a significant reduction in breast cancer cells growth and viability." (PMID 33916304, 2021). "TRPC6 expression has been found to be enhanced in breast tumoral samples from patients as well as in both luminal breast cancer cell lines and TNBC cell lines." (PMID 33380424, 2021). "Prospect studies based on our conclusion will validate the efficacy of overactivation of Orai and TRPC6 in breast cancer repression using in vivo models." (PMID 33916304, 2021). "In this aspect, Orai1, complexed with the SK3 channel, has been found to play a relevant role in breast cancer cell migration and inhibition of TRPC6/Orai1-mediated SOCE was found to attenuate breast cancer cell proliferation and migration." (PMID 33916304, 2021). "TRPC channels, including TRPC3, TRPC5, and TRPC6, are typical oncogenic proteins that can be used to diagnose breast cancer." (PMID 33806911, 2021). "TRPC6 expression has been found upregulated in breast cancer cell lines, MCF-7 and MDA-MB-231, compared with normal breast epithelial MCF10A cells." (PMID 32138386, 2020). "TRPC3, TRPC4, and TRPC6 expression was described in the human breast carcinoma cell lines, TD7, MCF-7, and MDA-MB-231." (PMID 32887395, 2020). "A previous study has reported the abnormal upregulation of TRPC3 and TRPC6 in breast cancer tissues from patients; the differential expression of TRPC3 in MCF-7 and MDA-MB-231 has attracted our attention." (PMID 31003514, 2019). "TRPC6 contributes to the proliferation of prostate cancer epithelial cells, human epithelial breast cancer cells, and human hepatoma cells." (PMID 31627357, 2019).
breast carcinoma (continued). "The present study identifies TRPC6 as an ion channel that plays a relevant role supporting breast cancer cell proliferation, migration and invasion." (PMID 30223530, 2018). "The present study demonstrates that TRPC6 plays an important functional role supporting a variety of breast cancer hallmarks, including proliferation, migration and “in vitro” invasion." (PMID 30223530, 2018). "We confirmed the role of TRPC6 in breast cancer cell migration and proliferation by expressing a pore-dead dominant-negative TRPC6 (TRPC6dn) mutant." (PMID 30223530, 2018). "In the highly metastatic breast cancer cell line MDA-MB-231 the predominant TRPC channels expressed were TRPC3 and TRPC6 (of longer splice form variants)." (PMID 19689790, 2009). "Protein expression of TRPC3 and TRPC6 in breast cancer cell lines appeared to be consistent with the PCR results." (PMID 19689790, 2009). "In breast cancer biopsy tissues TRPC6 was expressed and appeared to be the predominant TRPC channel expressed." (PMID 19689790, 2009). "Our data provides strong evidence that TRPC3 and TRPC6 form heteromutimeric channels in breast cancer epithelial cell line MDA-MB-231, which is consistent with previous reports of TRPC3/6 expression." (PMID 19689790, 2009). "We also extended our studies to examine TRPC6 expression at the protein levels in breast cancer tissues." (PMID 18452628, 2008). "We have previously reported that TRPC6 is the detectable member of the store-independent TRPC channels expressed in breast cancer cells." (PMID 18452628, 2008). "Our results indicate that TRPC6 channels are strongly expressed and functional in breast cancer epithelial cells." (PMID 18452628, 2008). "Clinically, TRPC6 mRNA and protein were elevated in breast carcinoma specimens in comparison to normal breast tissue." (PMID 18452628, 2008). "This study shows that TRPC6 is expressed in both the MCF-7 breast cancer cell line and in the primary cultures of breast cancer epithelial cells." (PMID 18452628, 2008). "Here we studied the expression and function of endogenous TRPC6 channels in a breast cancer cell line (MCF-7), a human breast cancer epithelial primary culture (hBCE) and in normal and tumour breast tissues." (PMID 18452628, 2008). "Moreover, in breast cancer cells, TRPC6 was shown to be required for the Tg-induced translocation of ORAI1 and ORAI3 channels to the membrane." (PMID 37108424, 2023). "Multiple zinc transporters (such as ZnT2, ZIP6/LIV1, ZIP7 and ZIP10), zinc-permeable ion channels (such as TRPC6, TRPM7, and TRPV6), as well as metallothionein were reported to be overexpressed in breast cancer, some of which are associated with breast cancer metastases and poor prognosis." (PMID 34627839, 2021). "Interestingly, while ppFurin expression in MDA-MB-231, BT20, and MDA-MB-435 cells repressed their ability to migrate or invade, ppFurin affected viability only in the two breast cancer cell lines where Orai and TRPC6 hyperactivation was observed." (PMID 33916304, 2021). "Silencing TRPC6 largely reduces proliferation, survival and migration in breast cancer cell lines, which might be due to reduced expression of ORAI1 and ORAI3 in TRPC6 deficient cells." (PMID 32211326, 2020). "Over-expressed TRPC6 was found to promote breast cancer cell growth and metastasis." (PMID 31003514, 2019). "Furthermore, TRPC3, as well as TRPC6, are up-regulated in breast cancer biopsies and the breast cancer cell lines MCF7 and MDA-MB-231 cells." (PMID 30223530, 2018). "In these cell lines, TRPC6 have been found to be required for cell growth; however, the molecular basis of the functional role for TRPC6 in breast cancer cells remained unknown." (PMID 30223530, 2018). "Our data demonstrate that TRPC6 is expressed and functional in breast cancer epithelial cells." (PMID 18452628, 2008). "In contrast, the breast carcinoma tissue specimens revealed a significant overexpression of TRPC6." (PMID 18452628, 2008).